MIR34B (microRNA 34b)
Synonyms: hsa-mir-34b; MIRN34B; miRNA34B; mir-34b
Gene: MicroRNA gene on chromosome 11 (111,512,938 to 111,513,021, forward strand). Ensembl gene ENSG00000207811.
Pathways (Reactome):
Signal Transduction: MAPK6/MAPK4 signaling; Pre-NOTCH Transcription and Translation
Immune System: Regulation of PD-L1(CD274) translation
Gene Ontology:
Biological process: miRNA-mediated post-transcriptional gene silencing
Homologues: Orthologues: chimpanzee ptr-mir-34b (100% identical), macaque mml-mir-34b (100% identical), guinea pig MIR34B (95% identical), dog MIR34B (94% identical), mouse Mir34b (94% identical), tropical clawed frog xtr-mir-34b-3 (68% identical), Caenorhabditis elegans cel-mir-34 (56% identical), Drosophila melanogaster mir-34 (56% identical), tropical clawed frog xtr-mir-34b-2 (55% identical). Paralogues in human: MIR34C (60% identical), MIR34A (51% identical).
Diseases named in the same sentence as MIR34B in open-access papers:
MIR34B is named in the same sentence as 7 diseases in open-access papers, as found by Europe PMC text mining. Sharing a sentence is not in itself a finding about the gene and the disease. The quoted sentences say what the papers report.
gastric cancer (1 paper, 2023). A primary or metastatic malignant neoplasm involving the stomach. "MiR-34b/c may be suppressed in gastric cancer by hypermethylation of MIR34B/C." (PMID 37443682, 2023).
prostate carcinoma (1 paper, 2023). A carcinoma that arises from epithelial cells of the prostate gland. "CpG hypermethylation of MIR34B suppresses miR-34b in prostate cancer." (PMID 37443682, 2023).
tumor (5 papers, 2013 to 2022). "Taken together, these results suggest that various molecular mechanisms concur to MYC activity in O1 tumours: genomic alterations, hypomethylation and down-regulation of its silencers mir34b and mir34c through hypermethylation of their promoter region." (PMID 27090007, 2016). "In line with what has been shown for other tumor suppressors, we observe that MIR34B/C undergo an epigenetic switch from polycomb mediated gene silencing to permanent gene silencing by DNA methylation during lymphomagenesis." (PMID 24722400, 2014). "For this purpose, we selected CpG sites within 200 bp from transcription start sites (TSS200) for two tumor-suppressor genes (cg22879515 (MIR34B), and cg23180938 (CDO1)), and assessed distributions of their β values obtained in the initial genome-wide methylation analysis." (PMID 24312652, 2013).
cancer (2 papers, 2013 to 2021). A tumor composed of atypical neoplastic, often pleomorphic cells that invade other tissues. "Pan-cancer analysis showed that MIR129-2, MIR149, MIR152, MIR150, MIR34B, and MIR34C were downregulated in at least four types of cancer, and MIR150 had a protective role against death in most types of cancer." (PMID 33403044, 2021). "Also, the methylation levels of two CpG sites in TSS200 of two tumor-suppressor genes (MIR34B and CDO1) were corrected, and some cancer samples showed almost complete methylation." (PMID 24312652, 2013).
MIR34B also shares sentences with these, for which no sentence is quoted: colon adenocarcinoma (1 paper); hematological cancers (1); metastatic tumors (1).